BRAF (B-Raf proto-oncogene, serine/threonine kinase)
Diseases named in the same sentence as BRAF in open-access papers (continued):
Sharing a sentence is not in itself a finding about the gene and the disease.
melanoma (continued). "In recent years, AI has been successfully used to predInict BRAF mutation status with high accuracy in human tumours, such as melanoma, thyroid carcinoma and colorectal carcinoma from radiological scans or WSIs." (PMID 37570213, 2023). "Among them, CYTL1 was highly expressed in melanoma, especially in BRAF-mutated melanoma, and the high expression of CYTL1 was associated with epithelial-mesenchymal transition (EMT), cell cycle, and cellular response to UV." (PMID 37745303, 2023). "The Food and Drug Administration (FDA) has approved MAPK inhibitors as a treatment for melanoma patients carrying a mutation in codon V600 of the BRAF gene exclusively." (PMID 37569660, 2023). "BRAF-mutated melanoma relapsing after targeted therapies is an aggressive disease with unmet clinical need." (PMID 36418472, 2023). "Mutations in the BRAF gene, especially the V600E mutation, have been identified in various types of cancer, including melanoma and NSCLC." (PMID 37444584, 2023). "Mutational inactivation of STAG2 is a major cause of the resistance of BRAF-mutant melanomas to BRAF/MEK inhibitors." (PMID 37479689, 2023). "A recent study shows that about 50% of melanoma patients carry a mutation of the BRAF protein, and roughly 75% of them (38% of all patients) received a BRAF inhibitor as a therapy." (PMID 37508582, 2023). "We have shown better short-term control of melanoma relapses when DT was used in patients with BRAF-mutated melanoma." (PMID 37686659, 2023). "Mutational profile of mucosal melanomas is known to differ from their cutaneous counterparts, suggesting a different pathway in the pathogenesis: They harbor lower BRAF and TERT, and relatively higher NRAS and KIT mutation frequencies." (PMID 35642348, 2023). "The presence of BRCA1/2 mutations in breast and prostate cancer, as well as BRAF mutations in melanoma, are other examples where molecular profiling can impact cancer therapeutics." (PMID 37368872, 2023). "In the melanoma population with BM and BRAF mutated tumors, the combination of immunotherapy with BRAF and MEK inhibitors has been tested in recent years, as well as the sequencing of these treatments." (PMID 38022574, 2023). "We previously observed that Nox4 expression in BRAF-mutated melanoma cells is related to their metastatic progression." (PMID 37189846, 2023). "Management of advanced melanoma remains challenging, with most BRAF (B-Raf proto-oncogene, serine/threonine kinase)-mutated metastatic patients relapsing within a few months upon MAPK inhibitors treatment." (PMID 37174717, 2023). "Of note, BRAF variations coexist with TERT promoter mutations both in melanoma and in thyroid cancer." (PMID 38033865, 2023). "In up to 90% of human melanoma, mutated BRAF or mutated NRAS hyperactivate the kinase ERK, according to the examination of genetic changes." (PMID 37569598, 2023). "Taken together, our results demonstrate that PHB ligands can overcome acquired resistance to combined BRAF/MEK inhibitors in BRAF-mutated melanoma." (PMID 37508519, 2023). "From this dataset we identified 2071 DEGs between BRAF mutated (all mutations) and wildtype melanomas (adjusted p-values < 0.05; false discoveries corrected using the Benjamini–Hochberg procedure)." (PMID 36539575, 2023). "Therapies targeting mutated BRAF are now a standard of care in a subset of patients with melanoma and lung cancer." (PMID 37240418, 2023). "The prognostic value was independent of the BRAF mutation status, as shown by the subgroup analysis of patients with either BRAF wild type or BRAF mutated melanoma." (PMID 37295047, 2023). "Our work is the first to show that Cdc42(G12V) enhances the carcinogenic potential of melanoma cells that harbour a BRAF mutation, the most common mutation seen in melanoma." (PMID 37114375, 2023). "In a similar vein, the REPOSIT study attempted to investigate ctDNA mutational markers of resistance to targeted treatment with BRAF/MEK inhibition in unresectable stage IIIc/IV melanoma." (PMID 38201222, 2023).
melanoma (continued). "Somatic mutations of the BRAF gene, causing constitutive activation of BRAF, have been found in various types of human cancers such as malignant melanoma, and CRC." (PMID 37768281, 2023). "More importantly, the scratch test demonstrated the efficacy of the Nox inhibitor (DPI) in blocking migration, supporting its use to counteract drug resistance and thus cell invasion and metastasis in BRAF-mutated melanoma." (PMID 37189846, 2023). "The BRAF-targeted therapy is used either alone or in combination with the MEK inhibitors such as trametinib, and binimetinib, which are associated with improved survival rates and increased therapeutic effect in patients with BRAF-mutated melanomas." (PMID 36649046, 2023). "In their study, Loria and colleagues observed that SEMA6A is partially engaged in the control of actin cytoskeleton remodeling of BRAF-mutated melanoma, which drives their fast rate of proliferation and survival." (PMID 38067240, 2023). "As a consequence of our results, patients with high eTILs and a relevant risk of relapse (IIB and above) or advanced melanoma patients (stage III/IV) should receive anti-PD-1 therapy for both BRAF wild type and BRAF-mutated melanoma." (PMID 37295047, 2023). "Triple wildtype (TWT) melanomas that lack mutations in BRAF, NRAS, or NF1 form 10% of human melanomas and are heterogeneous in their genomic drivers." (PMID 36901951, 2023). "Reinstalling nestin expression in drug resistant BRAF mutated melanoma cells strongly impairs their migration and invasion ability." (PMID 38008717, 2023). "According to the National Comprehensive Cancer Network guidelines for melanoma, anti-PD-1 monotherapy is the preferred regimen, and combination-targeted therapy is recommended as first-line therapy if BRAF V600-activating mutation is present." (PMID 37215493, 2023). "Other protein substitutions, available in V600K mutations (which account for around 20% of BRAF mutations responsible for early-stage melanoma development), are primarily observed in melanoma patients who have endured prolonged sun exposure." (PMID 37102943, 2023). "While short-term exposure of melanoma cells to BRAF inhibitors induces a notable increase in AR expression, this induction alone is insufficient to cause resistance to BRAF inhibitors, as it resulted instead from sustained AR expression." (PMID 37838724, 2023). "This concept is also supported by the DREAMseq trial demonstrating that patients with BRAF-mutated melanoma receiving first-line ICI and then targeted therapy had a better prognosis than those receiving initially targeted therapy and, subsequently, ICI." (PMID 37295047, 2023). "WES revealed only 12 shared somatic mutations among these tumors, including the BRAF V600E mutation, and other genes important in defining melanoma and continued activation of the MAPK pathway." (PMID 37398360, 2023). "Most patients with BRAF mutations usually initially show a response to BRAF inhibitors, but melanoma patients with BRAF mutations usually relapse only a few months after starting treatment." (PMID 37833287, 2023). "Results: 24 overlapping genes were identified by analyzing DEGs common to melanoma and normal tissue, BRAF-mutated and BRAF wild-type melanoma." (PMID 37745303, 2023). "Treatment of various BRAF-mutated melanoma cell lines with the BRAF inhibitor dabrafenib (GSE98314) reduced the expression of EZH2 and PLK1 in a comparable manner." (PMID 36768289, 2023). "Because these mutations lead to activation of the MAPK pathway, several BRAF (BRAFi) and MEK (MEKi) inhibitors have been developed to treat these tumors and in particular BRAF-mutated melanoma." (PMID 37296851, 2023).
melanoma (continued). "This is confirmed here for two BRAF-mutated melanoma cell lines at the levels of cell viability, cell proliferation, and apoptosis induction." (PMID 36902392, 2023). "BRAF class I mutations in melanoma cells are accompanied by the specific clinicopathological characteristics and aggressive behavior of melanomas." (PMID 36765875, 2023). "Patients with melanoma with BRAF V600E and V600K mutations respond to clinically available BRAF inhibitors." (PMID 36998456, 2023). "The phase III, IMspire150 or TRILOGY trial evaluated first-line vemurafenib and cobimetinib combined with either atezolizumab or placebo in 514 patients with unresectable stage IIIc–IV BRAF V600-mutated melanoma." (PMID 36995534, 2023). "Studies have also explored the relationship between TERT promoter mutations and other common genetic alterations in melanoma, such as BRAF and NRAS mutations." (PMID 37504268, 2023). "BRAF V600E Mutation in Melanoma: The BRAF V600E mutation in melanoma is a predictive biomarker for response to BRAF inhibitors (e.g., vemurafenib and dabrafenib) and MEK inhibitors (e.g., trametinib and cobimetinib)." (PMID 38202898, 2023). "For Chinese stage III melanoma with BRAF mutation, both novel targeted therapy and immunotherapy showed potential benefits in relapse‐free survival compared to observation only." (PMID 37016119, 2023). "Due to melanoma’s time-sensitive nature, LA must aim to provide early access to BRAF testing and consider mutational status within treatment decision making." (PMID 36998456, 2023). "Metastatic melanoma patients carrying a BRAFV600 mutation can be treated with a combination of BRAF and MEK inhibitors (BRAFi/MEKi), but innate and acquired resistance invariably occurs." (PMID 36692026, 2023). "Both PHB ligands JI130 and MEL56 induce dose-dependent apoptosis in a panel of representative melanoma lines harboring wild-type BRAF and NRAS (HBL, LND1, and MM162), BRAF mutation (MM074 and MM029) or NRAS mutation (MM165)." (PMID 37508519, 2023). "The use of BRAF inhibitors demonstrated the principle susceptibility of melanoma to antiproliferative and proapoptotic therapies, suggesting researchers should search for strategies to further sensitize melanoma cells for apoptosis induction." (PMID 36902392, 2023). "In melanoma, mutations in BRAF (50%−70%), NRAS (15%−30%), NF1, KRAS and HRAS (in 2 and 1% of patients, respectively), and KIT are responsible for MAPK dysregulation." (PMID 36844227, 2023). "We demonstrated that PD-L1 expression by either TPS or CPS, the line and agent of immunotherapeutic treatment, the histological melanoma subtype, and BRAF V600 mutation status were associated with response and/or overall survival after ICB treatment." (PMID 36980349, 2023). "Mutations of BRAF are the most prevalent genetic alteration in human melanoma, with ~50% of tumours expressing the BRAFV600E oncoprotein." (PMID 36678596, 2023). "Approximately 50% of patients with melanoma harbor a BRAF mutation and are eligible for targeted therapy with BRAF/MEK inhibitors (BRAFi/MEKi)." (PMID 37568570, 2023). "Following the improved survival of BRAF-positive patients in melanoma cancers, the characterisation of the genetic landscape of tumour types identified the BRAF V600 mutations in many non-melanoma cancers too20 associated with poor survival outcomes." (PMID 37217528, 2023). "Together, these data indicate that significant differences exist in the protein landscape expressed under identical cell culture conditions by A2058 and A375 human melanoma cells, both harboring the same BRAF(V600E)-activating mutation." (PMID 37445731, 2023). "Specifically, the expression level of MMP-2 has been shown to be associated with poor prognosis in patients carrying BRAF-mutated melanoma." (PMID 37507910, 2023).
melanoma (continued). "The mutations that lead to melanoma progression mainly affect the BRAF gene and its most common variant is the V600E substitution that activates the MAPK pathway, resulting in uncontrolled cell proliferation and inhibition of apoptosis." (PMID 36672229, 2023). "It is well established that this mutation activates BRAF and is oncogenic, and targeting BRAF V600E is an effective treatment strategy in melanoma." (PMID 38136350, 2023). "This question was answered by the prospective phase III RCT called DREAMseq that assessed the optimal sequence of treatments between ICI and TT for patients with advanced melanoma harboring a V600 BRAF mutation." (PMID 37025593, 2023). "Here, a role for KiSS1 as regulator of the cellular response to vemurafenib in melanoma cell lines all characterized by the BRAF V600E mutation has emerged." (PMID 37790750, 2023). "BRAF is one of the most frequently mutated genes in melanoma, with rates ranging from 20 to 80%, and the hotspot V600E mutation accounting for 60-80% of BRAF mutations." (PMID 37841001, 2023). "Despite targeted therapies against BRAF(V600E) mutation and immune checkpoint-blocking antibodies providing treatment options for patients, the heterogeneous nature of melanoma significantly limits treatment efficacy." (PMID 37760480, 2023). "The landscape of malignant melanoma treatment has witnessed a transformative shift with the emergence of targeted therapies directed against BRAF(V600E) mutation and immune checkpoint-blocking antibodies." (PMID 37760480, 2023). "Due to melanoma’s time-sensitive nature, LA countries must provide early access to BRAF testing in appropriate situations and for mutational status to be considered within treatment decision making." (PMID 36998456, 2023). "Responses were seen in 10 (15%) of 68 evaluable patients in the Q2D expansion phase, including in 8 of 16 (50%) patients with BRAF mutation-positive melanoma naïve to RAF and MEK inhibitors." (PMID 37219686, 2023). "Circulating BRAF splicing variants were present in the plasma of three out of 38 patients with progressive melanoma, and these splicing variants were associated with EVs." (PMID 36674479, 2023). "In fact, BRAF is an attractive therapeutic target for BRAFV600E melanoma because this mutation has been found in a high number of patients, respect to other variants like V600K, V600D and V600R." (PMID 37534247, 2023). "The discovery of small molecule inhibitors selective for mutated BRAF marked the beginning of a new era in melanoma therapy, exposing the MAPK signaling pathway as a very promising therapeutic target." (PMID 37464364, 2023). "BRAF, as the most commonly mutated gene, leads to a high mutation burden for patients with melanoma (approximately 50% of patients with metastatic melanoma have BRAF mutations)." (PMID 36653848, 2023). "Within the four major genetic subtypes of cutaneous melanomas, TERT promoter mutation is observed in 75% of tumors with BRAF mutation but only observed in 6.7% of TWT melanomas." (PMID 37239381, 2023). "We conducted a phase Ib dose-escalation trial of phenformin with standard dose dabrafenib/trametinib in patients with metastatic BRAF V600-mutated melanoma." (PMID 37930123, 2023). "Together, these results indicate that SR-4835 efficiently inhibits CDK12/13 activity in BRAF-mutated melanoma, which results in increased DNA damage and reduced cell proliferation." (PMID 38104154, 2023). "Following the discovery of BRAFV600 E/K as an oncogenic driver of somatic mutation in melanomas, targeted therapy involving BRAF and MEK inhibitors was developed." (PMID 37205993, 2023). "This study demonstrated that drug compounds colocalized with melanoma cells with a higher signal intensity in the BRAF mutated tissue than in the wildtype." (PMID 36982192, 2023).
melanoma (continued). "We have previously shown that SREBP-1-mediated fatty acid biosynthesis underlies therapy resistance in BRAF-mutant melanoma." (PMID 37072838, 2023). "This mutation scenario was also proven in our cohort, with melanomas in face and scalp mostly carrying BRAF V600K, NRAS and NF1 mutations, whereas only one out of eight patients (12.5%) carried the BRAF V600E mutation." (PMID 36765773, 2023). "On the other hand, the BRAF V600E mutation was present in nine cases of metastatic melanomas of the head and neck, with three cases testing positive for this mutation." (PMID 37649946, 2023). "While BRAF/MEK inhibitor combination therapy is well established in patients with V600E/K mutations, the clinical data for the ~5% of melanomas with non-V600 BRAF mutations mainly consists of case reports given their rarity and genetic heterogeneity." (PMID 37370834, 2023). "In our study, we used a proteomic approach-based IMS technology to investigate melanoma tissues carrying BRAF and NRAS mutations." (PMID 36982192, 2023). "In a cohort of V600E-BRAF-mutated melanoma patients, we showed that the TERT promoter mutation status and TERT expression tended to be associated with response to BRAF and MEK inhibitors." (PMID 37296851, 2023). "Another study evaluated the use of BRAF inhibitors in V600 BRAF-mutated melanoma that recurs with the resectable disease on or after adjuvant immunotherapy for resected stage III/IV disease." (PMID 36900226, 2023). "It enrolled untreated melanoma patients with CNS metastases ≥ 5 mm and performance status ≤ 2, either BRAF V600 wild-type or BRAF V600 mutation-positive, who had completed adjuvant anti-PD-L1 therapy or were symptomatic and/or corticosteroid-depended." (PMID 36995534, 2023). "In this study, TMB and BRAF mutation status were identified as independent, predictive factors for relapse-free survival in high-risk melanoma patients with adjuvant anti-PD-1 therapy." (PMID 35192052, 2023). "Combined BRAF/MEK-inhibition constitutes a relevant treatment option for BRAF-mutated advanced melanoma." (PMID 37760406, 2023). "Usually, the gain-of-function BRAF mutation found in GISTs is the V600E, which is a common driver of melanoma, papillary thyroid carcinoma, and several other malignant tumors." (PMID 37046734, 2023). "The pLGG cell lines with a BRAF V600E mutation showed BRAFi MSSs at the same level as BRAF-mutated melanoma cells and had significantly higher MSSs compared to the pLGG cell lines with a KIAA1549:BRAF-fusion." (PMID 37500667, 2023). "Acts on melanomas that have V600E or V600K mutations in the BRAF protein, as a potent inhibitor of BRAF through ATP competitive binding of the active conformation of BRAF kinase." (PMID 36675114, 2023). "To conduct our research, we took advantage of BRAF-mutated melanoma-resistant subclones derived from murine D4M cells, here obtained and characterized, and from the human A375 cell line previously established." (PMID 37372043, 2023). "The oncogenic human BRAF V600E mutation is highly recurrent in several cancers, particularly malignant melanoma (~50% of cases) and also thyroid and colorectal carcinoma." (PMID 37079639, 2023). "In our cohort, patients with melanoma of BRAF-positive mutational status were treated both with BRAF/MEKi and anti-PD1 drugs." (PMID 37686659, 2023). "In melanoma, BRAF activation and mutations in phosphoinositide 3-kinase (PI3K) can downregulate IFNAR1, which inhibits the tumor-suppressive role of IFN signaling." (PMID 37374093, 2023).